EHHADH (enoyl-CoA hydratase and 3-hydroxyacyl CoA dehydrogenase)
Diseases named in the same sentence as EHHADH in open-access papers (continued):
Sharing a sentence is not in itself a finding about the gene and the disease.
pregnancy disorder (1 paper, 2017). A disorder that is related to pregnancy. "Finally, we also identified five genes (PLCB1, LUM, ADCY7, IRF7, and EHHADH) that we predict to be important for pregnancy disorders and placenta development, although such links remains to be established." (PMID 29222466, 2017).
renal cell carcinoma (1 paper, 2024). "RCC4 cells are derived from human renal cell carcinoma and are VHL-mutated qPCR and Western blot analysis were performed to compare EHHADH mRNA and protein expression between VHL-mutated RCC4 cells (controls) and an RCC4 subline reconstituted with VHL, here referred to as RCC4+VHL cells." (PMID 38304003, 2024).
renal Fanconi syndrome (1 paper, 2021). "Two autosomal dominantly inherited forms of renal Fanconi syndrome illustrate how multifaceted mitochondrial pathology can be: Mutation of EHHADH, an enzyme in fatty acid metabolism, results in decreased ATP synthesis and a consecutive transport defect." (PMID 34349672, 2021).
renal fibrosis (1 paper, 2022). A final common manifestation of a wide variety of chronic kidney diseases characterized by glomerulosclerosis and tubulointerstitial fibrosis. "The knockdown of EHHADH led to the downregulation of fatty acid metabolic processes and the upregulation of inflammation, as well as proximal tubule cell injury, providing an important condition for the development of renal fibrosis." (PMID 36359901, 2022).
steatosis (1 paper, 2022). Increased lipid within the cytoplasm of cells. "Our results showed that LZG treatment obviously increased the expression of EHHADH, ACOX1, and CPT1 in the liver tissues of NAFLD mice and AML12 cells with steatosis." (PMID 35035496, 2022).
uterine cancer (1 paper, 2023). Primary or metastatic malignant neoplasm involving the uterine corpus and/or the cervix. "Mutations of PPP2R1A in uterine cancer affect oncogenic signaling and promote tumor cell growth, whereas EHHADH and ACAT1 are regulators of drug resistance in tumor cells; however, the role of VCP in cancer is unclear." (PMID 37373553, 2023).
tumor (16 papers, 2015 to 2025). "Higher expression and lower methylation of EHHADH were associated with longer survival of ccRCC patients and lower pathological tumor stage." (PMID 38304003, 2024). "We further explored the association between EHHADH, MICA, and phenotypic markers of macrophages through biostatistical analyses and experimental validation using clinical tumor tissue obtained from HCC patients." (PMID 40723248, 2025). "The underlying metabolic and molecular mechanisms revealed that MICA in tumor cells induced M2-like polarization through the PPAR/EHHADH pathway, which regulates the fatty acid oxidation (FAO) in macrophages." (PMID 40723248, 2025). "In this study, we have identified the functional regulation of FAO in HCC tumor cells and macrophages by the MICA-associated metabolic enzyme EHHADH and its upstream molecule PPAR-α." (PMID 40723248, 2025). "To confirm the role of MICA in tumor cells in inducing M2-like polarization through the PPAR-α/EHHADH pathway, we employed a co-culture model consisting of MICA+HCC cells and macrophages." (PMID 40723248, 2025). "We assessed the correlation between EHHADH expression, tumor purity, and the infiltration of immune cells in HCC using the TIMER database." (PMID 40723248, 2025). "To accomplish this, we utilized the TIMER 2.0 database to analyze the relationship between EHHADH expression, tumor purity, and macrophage infiltration." (PMID 40723248, 2025). "Survival analysis based on TCGA primary tumor RNA-sequencing (RNA-Seq) expression data and TCGA patient survival data showed that low/medium EHHADH expression correlated with poorer survival in ccRCC patients." (PMID 38304003, 2024). "It has been suggested that EHHADH affects T-cell function in tumor infiltration, affecting immune surveillance in cancer." (PMID 37379307, 2023). "The expression of GAD1 (r = -0.14, P = 9.2E-03) and SPP1 (r = -0.237, P = 8.32E-06) was negatively correlated, whereas EHHADH was positively correlated (r=-0.15, P =5.36E-03) with tumor purity." (PMID 34869039, 2021). "Taken together, these results suggested that WFS1 and EHHADH played a critical role in tumor immune escape, which was involved in the carcinogenesis of HCC." (PMID 34869039, 2021). "Our findings suggested that WFS1 and EHHADH played essential roles in tumor growth by triggering immune checkpoints in HCC, and are thus promising prognostic biomarkers for patients receiving immunotherapy." (PMID 34869039, 2021). "TIMER and GEPIA databases revealed that WFS1 was significantly positively correlated and EHHADH was negatively correlated with tumor immune cell infiltration and immune checkpoint expression." (PMID 34869039, 2021). "We have also confirmed the decreased expression of EHHADH in our collected tumor tissues." (PMID 40723248, 2025). "Importantly, adoptive transfer of T cells overexpressing gain-of-function candidates (AAK1ΔN125, SPRR1B, and EHHADH) into tumor-bearing mice resulted in increased T cell infiltration into tumors." (PMID 38143765, 2023). "In contrast, GOT2, EHHADH, and APOA1 were associated with better survival outcomes and were significantly downregulated in HCC tissues, as well as positively correlated with tumor stage, grade, age, and sex, suggesting that these three MRGs were tumor suppressor genes." (PMID 34869039, 2021). "Three hub genes (EHHADH, ACADM and AGXT2) were met the criterion of both WGCNA and PPI networks analysis, which showed highest negative association with pathological T stage (r = - 0.45, p = 0.01) and tumor grade (r = - 0.45, p = 0.01)." (PMID 31839812, 2019). "Furthermore, we found a pronounced decrease in EHHADH mRNA expression in advanced tumor stages." (PMID 40723248, 2025). "However, in late-stage HCC cells in co-culture models, MICA induces a decrease in EHHADH expression, leading to macrophage conversion to the anti-inflammatory M2-like phenotype, which may contribute to tumor progression." (PMID 40723248, 2025).
tumor (continued). "However, in late-stage HCC, MICA induces a decrease in EHHADH expression, leading to macrophage conversion to the anti-inflammatory M2-like phenotype, which may contribute to tumor progression." (PMID 40723248, 2025). "Subsequently, we utilized gene expression profiling interaction analysis (GEPIA), the cBio Cancer Genomics Portal (cBioportal), and the Tumor Immune Estimation Resource (TIMER) to assess the expression levels and prognostic significance of EHHADH." (PMID 40723248, 2025). "Conversely, tumor tissues exhibited significantly reduced expression of FDX1, CAT, and EHHADH than normal (p < 0.05)." (PMID 40109870, 2025). "The CPTAC mass spectrometry-based tumor proteome dataset, also available on the UALCAN website, revealed that EHHADH protein levels were significantly lower in primary ccRCC tissue than in normal kidney tissue." (PMID 38304003, 2024). "In tumor samples taken from the GSE45001 and GSE32879 datasets, seven genes (APOA2, CAT, ACOX1, APOE4, AGXT, EHHADH, and HSD17B4) showed a substantial downregulation." (PMID 38274331, 2024). "Analyzing data from The Cancer Genome Atlas (TCGA), Clinical Proteomic Tumor Analysis Consortium (CPTAC), and The Human Protein Atlas, this study shows that EHHADH expression is reduced in ccRCC and correlates with patient survival." (PMID 38304003, 2024). "Seven genes, PFKFB4, ALDOA, EGLN3, EHHADH, GAPDH, HMGCS2, and ENO2, related to tumor FDG uptake were revealed to have a good prognostic value for survival in HCC." (PMID 35174098, 2022). "GAD1, SPP1, and WFS1 were upregulated, whereas GOT2, EHHADH, and APOA1 were downregulated in HCC samples compared with peri-tumor controls, and this was consistent with the results in the ICGC, GSE14520, GSE54236, GSE107170, and GSE36376, validation datasets." (PMID 34869039, 2021). "In contrast, GOT2, EHHADH, and APOA1 were significantly negatively correlated with tumor infiltrating immune cells." (PMID 34869039, 2021). "Compared with peri-tumor samples, GAD1, SPP1, and WFS1 were significantly upregulated in tumor tissues, and GOT2, EHHADH, and APOA1 were significantly downregulated in tumor tissues." (PMID 34869039, 2021). "Although EHHADH has been proved to be closely related to tumor prognosis, its relationship with tumor immune cells has not been studied in depth." (PMID 40723248, 2025). "However, in the GSE32879 dataset, only seven genes (APOA2, CAT, ACOX1, APOE4, AGXT, EHHADH, HSD17B4) were observed to be significantly reduced in tumor samples." (PMID 38274331, 2024). "Our findings reveal a significant decrease in EHHADH gene expression in tumor tissues compared to adjacent non-cancerous tissues." (PMID 38637116, 2024). "Therefore, EHHADH, ACADM and AGXT2 could be suggested as protective tumor suppressors for ccRCC." (PMID 31839812, 2019).
cancer (10 papers, 2016 to 2025). A tumor composed of atypical neoplastic, often pleomorphic cells that invade other tissues. "In this study, we confirmed that the level of EHHADH protein was elevated in CDDP-R BC cell lines compared with parental cell lines, and that loss of EHHADH gene function significantly inhibited cancer cell proliferation, migration and invasion and increased the cells’ sensitivity to cisplatin." (PMID 33430801, 2021). "We first confirmed the targeting effect of miR-452-3p and miR-589-3p on ACACB and EHHADH in cancer cell lines using miRNA inhibitors." (PMID 40426998, 2025). "Subsequently, potential cancer-associated miRNA clusters upstream of ANGPTL1, SOCS3, ACACB, and EHHADH were predicted via integrated cross-analysis using multi-databases, including miRDB, TargetScan, RNAInter, and miRWalk." (PMID 40426998, 2025). "Combining the induction of MICA (pro-inflammatory effect) in cancer cells with the specific inhibition of EHHADH and FAO (anti-inflammatory effect) in macrophages may offer a beneficial therapeutic approach for HCC." (PMID 40723248, 2025). "Importantly, HCC patients with low EHHADH expression in cancer cells predicted poor prognosis." (PMID 40723248, 2025). "This study provides rationale for investigating all top gene candidates, and especially AAK1ΔN125, EHHADH, and SPRR1B, for therapeutic consideration in cancer immunotherapy." (PMID 38143765, 2023). "Given the functional relevance of EHHADH as an enzyme involved in FAO, our initial investigation focused on examining the differential expression of EHHADH mRNA in pan-cancer samples (33 cancer types) compared to normal tissues." (PMID 40723248, 2025). "EHHADH has not been extensively studied, but it shows differential expression in tumors compared to normal tissues, with increased or decreased levels depending on the type of cancer." (PMID 38304003, 2024).
infection (2 papers, 2021 to 2022). The state of being infected such as from the introduction of a foreign agent such as serum, vaccine, antigenic substance or organism. "A common motif comprised of the genes IKBKE, C1QBP, and EHHADH was found to be directly connected to the HNF4A hub in the infection tolerant state associated with A. baumanii and K. pneumoniae infection." (PMID 35706367, 2022). "As previously demonstrated, infection causes significant recruitment of SIRT2 to the TSSs of MYLIP, ERRC5, LEF1, SYDE2 and EHHADH but not ARAP2." (PMID 34929015, 2021).
heart (1 paper, 2021). "The metabolic network of butanoate metabolism involved ALDH5A1 and EHHADH, which could contribute to myocardial tissue damage in cyanotic congenital heart of ToF." (PMID 35174118, 2021).
kidney disease (1 paper, 2024). "We also examined the expression of EHHADH in a public database to determine the relationship between EHHADH and kidney disease." (PMID 38879653, 2024).
EHHADH also shares sentences with these, for which no sentence is quoted: Obesity (4 papers); rickets (3); chronic kidney disease (2); colon carcinoma (2); diabetes (2); fatty liver (2); Mitral regurgitation (2); 3MC syndrome (1); cardiomyopathy (1); cardiovascular disease (1); end-stage renal disease (1); Epileptic encephalopathy (1); Fanconi renotubular syndrome 3 (1); Gitelman syndrome (1); glioma (1); heart failure (1); Hypercalciuria (1); hyperlipidemia (1); hypophosphatemic rickets (1); LCHAD deficiency (1); leptospirosis (1); liver fibrosis (1); lung carcinoma (1); metabolic acidosis (1); microcephaly (1); neurological diseases (1); osteosarcoma (1); prostate tumors (1); renal tubular acidosis (1); schizophrenia (1).
A further 1 disease shares a sentence with EHHADH in 1 paper.